RN7SKP76 (RN7SK pseudogene 76)
Gene: Miscellaneous RNA gene on chromosome 16 (61,743,154 to 61,743,476, reverse strand). Ensembl gene ENSG00000201289.
Homologues: Orthologues: chimpanzee 7SK (99% identical). Paralogues in human: 7SK (86% identical), RN7SKP187 (81% identical), RN7SKP48 (80% identical), RN7SKP185 (80% identical), RN7SKP118 (80% identical), RN7SKP178 (78% identical), RN7SKP62 (78% identical), RN7SKP227 (77% identical), RN7SKP55 (76% identical), RN7SKP174 (76% identical), RN7SKP292 (76% identical), RN7SKP104 (73% identical), and 284 more.